ABCG1 (ATP binding cassette subfamily G member 1)
Diseases named in the same sentence as ABCG1 in open-access papers (continued):
Sharing a sentence is not in itself a finding about the gene and the disease.
diabetes (33 papers, 2011 to 2025). "ABCG1 plays a role in regulating blood sugar levels, hence its downregulation indicated to the researchers an increased risk of diabetes." (PMID 40943351, 2025). "Methylation changes in immune-related genes (e.g., TXNIP, ABCG1) have been associated with inflammatory pathways, insulin signaling, and glucose metabolism, thereby contributing to diabetes progression." (PMID 40380284, 2025). "It has been shown that, for example, DNA methylation levels at the CpG13 and CpG14 ABCG1 loci and increased methylation of the CpG15 locus are positively associated with the risk of developing type 2 diabetes mellitus." (PMID 39857239, 2024). "A number of studies have shown that ABCG1 methylation levels are associated with type 2 diabetes mellitus." (PMID 39857239, 2024). "For example, a nested case-control study found that methylation of cg06500161 at ABCG1 was associated with incident diabetes in a population of adults in rural China." (PMID 37779905, 2023). "ABCG1 has been associated with diabetes and metabolic syndrome." (PMID 38350951, 2024). "Deficit of both ABCA1 and ABCG1 leads to more significant β-cell function abnormalities than either transporter alone, leading to dyslipidemia and diabetes." (PMID 38532421, 2024). "IGLJ3, DNASE1L3, ABCG1, DPEP2, and KIF19 are highly differentiated genes associated with diabetes and periodontitis." (PMID 38532421, 2024). "The CpG cg06500161, annotated to the gene ABCG1, which was one of the overlapping DMPs between fasting glucose and HOMA-IR, was in the top five DMPs for incident diabetes, showing a strong positive association." (PMID 36529747, 2022). "The two top signals for incident diabetes, annotated to genes SREBF and ABCG1, were also associated with IFG, with hazard ratios (95% CI-s) 2.4 (1.2, 5.1) and 1.9 (1.1, 3.6), respectively." (PMID 36529747, 2022). "Among diabetes-free participants in ALSPAC, ABCG1 was positively associated with BMI, waist-circumference, fasting insulin, HOMA scores, CRP and triglyceride levels, but negatively associated with HDL levels." (PMID 33622391, 2021). "As expected, many genes merely changed in the sDM group, such as SULF2, GFAP, ABCG1, GCK, ISM1, and CORIN, have been associated with diabetes." (PMID 34880765, 2021). "Specifically, it should be noted that ABCG1, ABCA1 and ACSL3 were negatively, while KAT2B positively, associated with all signatures of statin use, CpG methylation and diabetes risk/status." (PMID 32612641, 2020). "Other studies have reported a link between ABCG1 downregulation and diabetes incidence and high fasting glycaemia." (PMID 32410704, 2020). "However, genotyping of two functional ABCG1 SNPs (rs1378577, −134 T > G and rs1893590, −204 A > C in the promoter region) in 1320 French morbidly obese patients (BMI > 40 kg/m2) revealed that those two SNPs were associated with BMI after adjustment for diabetes and HOMA-IR." (PMID 28869506, 2017). "Additional investigations in appropriate mouse models are therefore required in order to evaluate the overall physiopathological consequences of the reduced Abcg1 expression in diabetes." (PMID 28869506, 2017). "Further analysis indicated that hypermethylation of the ABCG1 promoter gene was associated with an increased risk of CHD after adjustment for age, gender, smoking, lipid levels, hypertension and diabetes." (PMID 28869506, 2017). "Our findings show that epigenetic markers associated with measures of glucose metabolism can be detected in whole blood samples, and they confirm previous evidence that ABCG1 is involved in diabetes either directly or indirectly." (PMID 27019061, 2016). "Much evidence indicates that the level of the scavenger receptor CD36 increases and those of ABC transporters (such as ABCA1 and ABCG1) decrease significantly in patients with diabetes and vascular complications thereof, such as atherosclerosis." (PMID 26807573, 2016).
diabetes (continued). "Secondly, inducing diabetes with streptozotocin significantly reduced renal expression of not only ABCA1 but also ABCG1 and SR-BI, and these changes preceded the development of diabetic nephropathy." (PMID 25181357, 2014). "Our results indicated a significant statistical association of promoter methylation of the ABCG1 gene with increased risk of CHD (OR = 19.966; 95% CI, 7.319–54.468; P*<0.001; P*: adjusted for age, gender, smoking, lipid level, hypertension, and diabetes)." (PMID 25084356, 2014). "Additionally, 7 CpG sites annotated to MAN2A2, ABCG1, DENND3, NCOR2, BAIAP2 and CPT1A were linked to changes in diabetes status." (PMID 39827095, 2025). "It would be of interest to evaluate whether patients with metabolic syndrome or diabetes who show low expression of Abca1/Abcg1 in monocytes due to hyperglycemia also show low Abca1/Abcg1 expression in bladder SMCs." (PMID 39931819, 2025). "The overall rather moderate deterioration of glucose homeostasis and diabetes risk could indicate a compensatory cholesterol export via ABCA1 and ABCG1." (PMID 36527064, 2022). "Similarly, mice with β-cell-specific deletion of Abca1 displayed impaired glucose tolerance, which worsened to substantial islet inflammation and diabetes in mice with additional deletion of Abcg1." (PMID 36527064, 2022). "Finally, the direction of association for CPT1A, ABCG1, SOCS3, TXNIP and SREBF1 was consistent with that reported in the literature for MetS and/or diabetes." (PMID 34780523, 2021). "However, it is still difficult to evaluate the impact of the impaired insulin secretion consecutive to Abcg1 deficiency in diabetes since glucose intolerance was not a common feature in Abcg1−/− mice." (PMID 28869506, 2017). "There was a significant statistical association of the promoter hypermethylation of the ABCG1 gene with CHD risk (OR = 22.859; 95% CI, 8.989–58.135; p<0.001 and OR = 19.966; 95% CI, 7.319–54.468; P*<0.001; P*: adjusted for age, gender, smoking, lipid level, hypertension, and diabetes)." (PMID 25084356, 2014). "It has been reported that, in diabetes, increased scavenger receptor of modified LDL (CD36) and reductions in the levels of ATP binding cassette (ABC) transporters (ABCA1 and ABCG1), increase macrophage foam cell formation." (PMID 26807573, 2016). "Inducing diabetes with streptozotocin significantly reduced renal expression of ABCA1, ABCG1 and SR-BI." (PMID 25181357, 2014). "Dyslipidaemia and diabetes are closely related, and epigenome-wide approaches have identified differential methylation of genes known to have a key role in lipid metabolism and lipid traits, particularly CPT1A, ABCG1, SREBF1." (PMID 39827095, 2025). "Although analysis of genetic variations in ABCG1 failed to report any relationship between ABCG1 and diabetes, numerous studies highlighted a link between epigenetic modulation of ABCG1 and IR and diabetes." (PMID 28869506, 2017). "Firstly, we found that 26.9% of the participants with ABCG1 gene promoter hypermethylation have diabetes, while only 6.5% of the participants without hypermethylation have it." (PMID 25084356, 2014). "This study found that 82.8% of the participants with ABCG1 gene promoter hypermethylation have CHD, while only 17.4% of the participants without hypermethylation have it; the percentage of the participants have diabetes is 26.9% in the former group and 6.5% in the latter group." (PMID 25084356, 2014). "Notably, among the seven CpG sites liked to the diabetes progression, five showed a negative correlation with gene expression levels, including cg23436042, cg11183227 (MAN2A2), cg06500161 (ABCG1), cg06710464 (BAIAP2), and cg17058475 (CPT1A), while cg08788930 (DENND3) and cg11311053 (NCOR2) did not." (PMID 39827095, 2025).
diabetes (continued). "Using a mouse macrophage cell line (RAW 264.7) and primary bone marrow derived macrophages (BMDMs) cultured in normal or diabetes relevant high glucose conditions we found that high glucose inhibits the LXR-dependent expression of ATP-binding cassette transporter A1 (ABCA1), but not ABCG1." (PMID 26288135, 2015).
type 2 diabetes (27 papers, 2016 to 2025). "The replicated associations for type 2 diabetes implicated genes including ABCG1, CPT1A, SREBF1, and TXNIP." (PMID 37410739, 2023). "Hypomethylation within TXNIP (cg19693031) and ABCG1 hypermethylation (cg06500161) have been associated with type 2 diabetes risk across individuals of multiple ancestries." (PMID 37410739, 2023). "We have also previously reported that the expression of ABCG1 was significantly reduced in monocytes in patients with type 2 diabetes and was associated with impaired cholesterol efflux, whereas no changes were seen in ABCA1 and SR-B1 compared with controls." (PMID 37094639, 2023). "A nested case-control study including 25,372 individuals identified five loci that were associated with future type 2 diabetes incidence, including ABCG1, PHOSPHO1, SOCS3, SREBF1, and TXNIP." (PMID 35399937, 2022). "Studies demonstrated an association between higher ABCG1 methylation and an increased risk of coronary heart disease, type 2 diabetes, and metabolic syndrome." (PMID 35551677, 2022). "In light of the identified GPS2-ABCG1 pathway, it is of interest that DNA methylation at the ABCG1 locus is associated with an increased risk of developing type 2 diabetes." (PMID 32798719, 2020). "In summary, we report DNA methylation site cg06500161 at ABCG1 as a mediator of the association between statins and type 2 diabetes." (PMID 32612641, 2020). "Firstly, we have shown that statin use was associated with DNA methylation modifications of ABCG1 and such methylation patterns are correlated with the risk of type 2 diabetes." (PMID 32612641, 2020). "Next, based on transcriptome analysis, we determined the links between the medication-associated epigenetic status of ABCG1 and biological pathways on the pathogenesis of type 2 diabetes." (PMID 32612641, 2020). "Because epigenetic analysis of other cohorts identified associations between DNA methylation at ABCG1 and type 2 diabetes phenotypes, we tested both cg06500161 and cg05639842 for association with type 2 diabetes in the FHS cohort." (PMID 32612641, 2020). "Our results showed that DNA methylation levels at cg06500161 of ABCG1 were positively associated with the use of statin, type 2 diabetes and related traits (fasting glucose and insulin) in FHS and WHI." (PMID 32612641, 2020). "ABCG1 CpG sites associated with type 2 diabetes, fasting glucose and fasting insulin in participants from the FHS and WHI studies." (PMID 32612641, 2020). "Our findings imply that statin use mediates DNA methylation at cg06500161 of ABCG1 and this contributes to increased risk of type 2 diabetes." (PMID 32612641, 2020). "We determined the association between the statin use, DNA methylation at ABCG1 and type 2 diabetes/glycemic traits in the Framingham Heart Study Offspring (FHS, n = 2741), with validation in the Women’s Health Initiative Study (WHI, n = 2020)." (PMID 32612641, 2020). "We concluded that DNA methylation site cg06500161 at ABCG1 is a mediator of the association between statins and risk of type 2 diabetes." (PMID 32612641, 2020). "Epigenome-wide association studies in several cohorts have shown strong associations between DNA methylation at CpG sites in ATP binding cassette subfamily G member 1 (ABCG1) and risk of type 2 diabetes." (PMID 32612641, 2020). "This study aims to examine the epigenetic mechanisms of ABCG1 through which statin use associates with risk of type 2 diabetes." (PMID 32612641, 2020). "From our CpG sites related to MetS, there was one hit cg06500161 (ABCG1), associated with MetS, BMI, and type 2 diabetes in this database." (PMID 31796056, 2019). "After adjustment for BMI, only the CpG site in ABCG1 remained significantly associated with type 2 diabetes, while for all other CpGs effect sizes became smaller and were no longer significant." (PMID 29164275, 2018).
type 2 diabetes (continued). "In this study, we replicated five CpGs in blood, from which four reside in the genes previously shown to be associated with type 2 diabetes (ABCG1, LOXL2, SLC1A5, SREBF1)." (PMID 29164275, 2018). "Impaired monocyte cholesterol efflux in type 2 diabetics was linked to ABCG1 gene expression." (PMID 37672078, 2023). "Furthermore, a prospective study in Finland on non-diabetic population showed DNA methylation of SREBF1 and ABCG1 genes were associated with HbA1C, glucose levels and type II diabetes risk." (PMID 35655232, 2022). "The mechanisms of genetic variants on ABCG1 and type 2 diabetes remain unclear and controversial, suggesting that epigenetic processes might be involved in the regulation of ABCG1 and downstream gene expression, and ultimately diabetic signatures." (PMID 32612641, 2020). "To date, only one longitudinal EWAS study focusing on type 2 diabetes has been published, identifying five CpGs associated with disease onset in Indian Asians during the follow-up period, two of which (the CpGs in ABCG1 and PHOSPHO1) were replicated in a prospective study." (PMID 29164275, 2018). "In our Lifelines sample, five out of 52 included CpGs showed significant associations with type 2 diabetes (the Bonferroni-adjusted p < 0.0009 (0.05/52 CpGs)), including the loci in the ABCG1, LOXL2, TXNIP, SLC1A5 and SREBF1 genes (see a short description in ESM Box 1)." (PMID 29164275, 2018). "For example, some of our loci, mapping to ABCG1, CPT1A and TXNIP, have been associated with lipid and metabolic traits such as triglycerides, BMI, and type 2 diabetes." (PMID 41361833, 2025). "Genes annotated to CpGs that were associated with type 2 diabetes included ABCA1, ABCG1, CPT1A, SREBF1, SLC7A11, SLC7A5, and TXNIP among others (see S12 Table for full details)." (PMID 37410739, 2023). "We and others have previously shown that the expression of ABCG1 in monocytes was reduced in patients with type 2 diabetes, and increased intracellular lipid accumulation has been attributed to the decrease in ABCG1 expression and cholesterol efflux." (PMID 37094639, 2023). "For four of the top six CpGs previously identified in a meta-EWAS of type 2 diabetes that had bidirectional 2SMR data (CpGs in TXNIP, HDAC4, SYNM and ABCG1), the observational and causal effects were consistent only at HDAC4 (cg00144180)." (PMID 37202507, 2023). "The results from our meta-analysis included CpG sites at genes that are known to be associated with type 2 diabetes, such as TXNIP, ABCG1, SREBF1 and CPT1A, showing consistency between cross-sectional and longitudinal studies and also between ethnicities." (PMID 35169870, 2022). "In both studies, increased methylation in the ABCG1 and SREBF1 genes and decreased methylation in the TXNIP gene at baseline were associated with incident type 2 diabetes." (PMID 35169870, 2022). "Our results and those of others show that increased DNA methylation at ABCG1 was positively associated with diabetic signatures providing substantial evidence in support of these correlations between ABCG1 and type 2 diabetes from an epigenetic perspective." (PMID 32612641, 2020). "•GPS2 and ABCG1 levels in omental adipose tissue inversely correlate with type 2 diabetes in obese humans." (PMID 32798719, 2020). "It has been recently shown that methylation changes of the CpGs located in SREBF1, ABCG1 and CPTA1 were not only associated with type 2 diabetes but also with BMI." (PMID 29164275, 2018). "Results from the majority of those studies indicate that differentially methylated sites in the TXNIP, ABCG1, CPT1A and SREBF1 genes are associated with type 2 diabetes and glycaemic traits." (PMID 29164275, 2018). "The authors estimated that 32% of the unexplained risk for future type 2 diabetes among Indian Asians compared with controls was associated with a higher methylation score based on the top five markers at TXNIP, ABCG1, SREBF1, SOCS3 and PHOSPHO1." (PMID 29164275, 2018).
type 2 diabetes (continued). "ABCG1 expression has been found to be decreased in type 2 diabetes." (PMID 39857239, 2024). "Adjustment for baseline BMI (model 2) and for BMI, smoking and follow-up time (model 2.1) revealed that the number of significant DMS associated with incident type 2 diabetes decreased from 76 to 4 and 3, respectively (still including the two top CpG sites at the TXNIP and ABCG1 genes)." (PMID 35169870, 2022). "The association of ABCG1, SREBF1, and TXNIP with the incidence of type 2 diabetes could be reaffirmed in an independent replication study, thus rendering these factors promising for clinical use as biomarkers." (PMID 35159278, 2022). "Decreased ABCG1 expression has been found in skeletal muscle from subjects with type 2 diabetes." (PMID 32612641, 2020). "Coding SNPs in ABCG1 were found not to be associated with risks for type 2 diabetes in the Copenhagen General Population Study." (PMID 32612641, 2020). "Previous GWAS have reported negative results in the associations between ABCG1 and risk for type 2 diabetes." (PMID 32612641, 2020). "Additionally, our results are consistent with a recent study of epigenetic determinants of type 2 diabetes in Mexican-Americans, showing differential DNA methylation levels at ABCG1." (PMID 29643945, 2018). "Furthermore, type 2 diabetes patients showed low expression of ABCG1 and increased intracellular cholesterol accumulation." (PMID 27777315, 2016). "A family-based study of 859 Mexican Americans showed that the degree of methylation at top regions including TXNIP, ABCG1 and SAMD12 genes and two intragenic regions accounted for 7.8% of the heritability of type 2 diabetes in Mexican Americans." (PMID 29164275, 2018). "An EWAS of BMI reported differential methylation at CPT1A and ABCG1, and an EWAS of type 2 diabetes at SREBF1 and ABCG1." (PMID 27350042, 2016). "Furthermore, CpGs annotated to ABCG1, DHCR24, and MYLIP were common to ischemic heart disease and type 2 diabetes." (PMID 37410739, 2023). "Hence, another 47 patients with type 2 diabetes were recruited, and IDOL and ABCG1 expression was determined to evaluate the contribution of IDOL and ABCG1 to intracellular lipid accumulation." (PMID 37094639, 2023). "Similarly, a methylation score based on five markers located in ABCG1, PHOSPHO1, SOCS3, SREBF1, and TXNIP could predict future type 2 diabetes incidence independent of established risk factors." (PMID 35159278, 2022). "Recent epigenome-wide association studies (EWASs) in blood have identified differentially methylated CpG sites (DMS), in individuals with vs without type 2 diabetes, in genes such as TXNIP, ABCG1 and SREBF1." (PMID 35169870, 2022).